FANK1 (fibronectin type III and ankyrin repeat domains 1)
Description:
Through the activation of JUN and AP-1-mediated transcription, may regulate apoptosis.
Synonyms: HSD13
Tractability: PROTAC: UniProt records ubiquitination sites on it.
Gene: Protein-coding gene on chromosome 10 (125,896,538 to 126,009,595, forward strand). Ensembl gene ENSG00000203780.
Subcellular location: Nucleus; Cytoplasm, cytosol; Cytoplasm, cytoskeleton, cilium basal body; Cell projection, cilium
Subcellular location (Human Protein Atlas): Nucleoplasm
Gene Ontology:
Molecular function: protein binding
Biological process: negative regulation of apoptotic process; positive regulation of apoptotic process; positive regulation of DNA-templated transcription
Cellular component: chromatin; cytoplasm; cytosol; nucleoplasm; nucleus; ciliary basal body; cilium; ciliary base
Genetic constraint (gnomAD): Loss-of-function variants: 46 observed, 46.42 expected, observed/expected ratio (o/e) 0.99, 90% interval 0.78 to 1.27. The upper end of that interval is the gene's LOEUF score, 1.27, which puts it in group 5 of 6, group 1 being the genes least tolerant of losing a copy. Missense variants: 391 observed, 443.16 expected, observed/expected ratio (o/e) 0.88, 90% interval 0.81 to 0.96. Synonymous variants: 149 observed, 160.3 expected, observed/expected ratio (o/e) 0.93, 90% interval 0.81 to 1.07.
Homologues: Orthologues: chimpanzee FANK1 (99% identical), pig FANK1 (92% identical), dog FANK1 (91% identical), mouse Fank1 (88% identical), macaque FANK1 (88% identical), guinea pig FANK1 (88% identical), rat Fank1 (88% identical), rabbit FANK1 (77% identical), tropical clawed frog fank1 (60% identical), zebrafish fank1 (52% identical).
Diseases named in the same sentence as FANK1 in open-access papers:
FANK1 is named in the same sentence as 4 diseases in open-access papers, as found by Europe PMC text mining. Sharing a sentence is not in itself a finding about the gene and the disease. The quoted sentences say what the papers report.
atherosclerosis (1 paper, 2020). A disease characterized by the build-up of fatty material and calcium deposition in the arterial wall resulting in partial or complete occlusion of the arterial lumen. "Further studies are required to investigate the changes in promoter methylation in NETO1, FANK1, and SERHL2 in the development of atherosclerosis." (PMID 32398127, 2020).
cancer (3 papers, 2017 to 2022). A tumor composed of atypical neoplastic, often pleomorphic cells that invade other tissues. "In addition, 1 SNP was detected in KMT2C, a BC oncogene, and 9 others were detected in or near 10 genes (SERAC1, DAGLB, MACF1, NVL, FBXW4, FANK1, KCTD4, CAVIN1; ATP6V0A1 and ZBTB20-AS1) previously associated with non-BC cancers." (PMID 35589867, 2022).
tumor (3 papers, 2017 to 2022). "FANK1 was recently identified as a novel binding partner in mammalian cells that prevents the proteasome degradation of polyubiquitinated FANK1, which leads to the activation of the AP-1 signaling pathway and the induction of tumor cell apoptosis." (PMID 35589867, 2022). "The deregulation of both FANK1 and KCTD4 may be a consequence of the observed somatic variants, thus suggesting another association with tumor development and their use as an early detection biomarker in a cfDNA-based assay." (PMID 35589867, 2022). "Additionally, RYBP both interacts with and up‐regulates fibronectin type III and ankyrin repeat domains 1 (FANK1) protein in tumour cells to induce apoptosis via the JNK‐AP1 signalling pathway." (PMID 29383875, 2018).
FANK1 also shares sentences with these, for which no sentence is quoted: asthma (1 paper).